ELN (elastin)
Diseases named in the same sentence as ELN in open-access papers (continued):
Sharing a sentence is not in itself a finding about the gene and the disease.
tumor (continued). "MMP9 is the most versatile of the MMPs and can degrade various elements of the tumour microenvironment, like elastin, fibrillin, laminin, gelatin and collagens of type IV, V, XI and XVI52,54." (PMID 29743718, 2018). "We show that the presented DNA aptamers have different binding to various lung tumor structures, such as elastic fibers, tumor cells, blood vessels, and elastin, all of which play important roles in tumor progression." (PMID 28325282, 2017). "Lysyl oxidase (LOX) catalyzes the formation of lysine-derived cross-links in collagen and elastin and it is involved in several other biological functions (e.g. development, tumor suppression, cell motility and cellular senescence)." (PMID 28719655, 2017). "Tumor cells are surrounded by layers of extracellular matrix (ECM) proteins (e.g., collagen, elastin, fibronectin, and laminin), which largely prevents the tumor vasculature from penetrating the tumor nests." (PMID 27275358, 2016). "Two features reaching the highest kappa value in the study were either a rim of elastin or D2-40 marking cells covering more than 50 % circumference of a tumour cluster." (PMID 27173782, 2016). "High amounts of elastin favor resistance for tumor cell migration, whereas high collagen and organized oriented deposition promote tumor cell migration." (PMID 27018053, 2016). "Elastin and its peptides are factors involved in tumor invasion, because these molecules are known to stimulate receptor signaling and chemotaxis." (PMID 26042506, 2015). "There are limited data on the role of elastin and its receptors in tumor invasion, but they are disorganized in the stroma of prostate cancer." (PMID 26042506, 2015). "3D environments containing relevant structural proteins (collagens, laminin, elastin), as well as defined tissue organization appropriate to site of tumor growth in vivo, are important considerations for recapitulating tumor cell behavior." (PMID 24724052, 2014). "At our institution, elastin trichrome stains are performed on a minimum of five tumor-containing blocks per case." (PMID 25601902, 2014). "Tumor angiogenesis, chicken angiogenesis, and mesenteric angiogenesis data suggest that elastin and elastin degradation products play a key role in vascular morphogenesis." (PMID 24949484, 2014). "MMP-10, one of the lesser studied MMPs, is limited to epithelial cells and can facilitate tumor cell invasion by targeting collagen, elastin and laminin." (PMID 24885595, 2014). "Fibroblasts produce a number of growth factors (including FGF, EGF, PDGF, and TGF-β), and ECM components (such as collagen, elastin and proteoglycans), which serve in wound and tumor stroma formation." (PMID 24274644, 2013). "On the other hand, the tumor is characterized by a TPEF intensity that is lower than the TPEF signal of elastin fibers and some skin appendages, e.g., sebaceous glands, but higher than for the rest of the adjacent dermal tissue." (PMID 27429131, 2013). "Reports have shown that cathepsin S is stable at neutral pH and is potently elastin- and collagenolytic, promoting extracellular matrix remodelling, tumor growth and invasion in the tumor microenvironment." (PMID 22168338, 2011). "LOX encodes an extracellular copper-requiring enzyme that initiates collagen and elastin crosslinking and enhances tumor cell invasion and metastasis." (PMID 21731642, 2011). "The generated bioactive elastin-derived peptides (EDPs) are thought to contribute to tumour progression." (PMID 20959825, 2010). "A marked increase in elastin deposition was observed in the tumor areas." (PMID 40895158, 2025). "Besides, we observed a significant reduction in collagen and elastin density within the tumor tissue, concomitant with an increased linearity of collagen fibers." (PMID 39744437, 2025). "Our findings revealed significant elastin deposition (elastosis) in tumor tissues." (PMID 40895158, 2025).
tumor (continued). "In this context, it is interesting to note the pro-tumor properties of elastin, which, in CRC, could regulate adhesion, migration, and invasion." (PMID 40141206, 2025). "HSBP1 can inhibit elastin-induced ferroptosis in tumor cells." (PMID 40128669, 2025). "We hypothesized that tumor samples exhibit elevated elastin accumulation, a phenomenon known as elastosis." (PMID 40895158, 2025). "Furthermore, these amine oxidases enhance collagen and elastin crosslinking in the tumor extracellular matrix, favoring cell motility and metastasis advancement." (PMID 38822944, 2024). "Ferroptosis inducers such as elastin and sorafenib can directly induce ferroptosis in tumor cells by interfering with intracellular iron metabolism and lipid peroxidation pathways, leading to tumor cell death." (PMID 39273090, 2024). "Moreover, the up-regulation of PPAR β/δ was associated with the increased expression of both ANGPTL4, a PPAR β/δ target gene involved in angiogenesis and tumor development, and the extracellular matrix proteins elastin, collagen 3α, and fibronectin." (PMID 37048084, 2023). "Using an elastin stain can also help differentiate between arteries and veins when the histologic sample does not portray apparent determining factors and, thus, invasion by the tumor cells." (PMID 37894944, 2023). "The IHC staining analysis illustrated an elevated level of ELN in tumor tissues." (PMID 37441420, 2023). "Preventing the degradation of elastin might therefore block positive inflammatory tumor feedback and may result in reduced cancer progression and metastasis." (PMID 37001705, 2023). "Among them, MMP2 and MMP9 could degrade type IV collagen, elastin, gelatin and other components, directly destroy the extracellular matrix barrier and promote tumor metastasis." (PMID 35332127, 2022). "It mainly includes tumor cells, tumor stem cells, endothelial cells, fibroblasts, immune cells, extracellular matrix structural components (such as collagen and elastin, among others) locally secreted cytokines, peptide growth factors, and other soluble substances." (PMID 36338717, 2022). "We observed strong correlation between the abundance of several microbes with elastin expression as well as genes that regulate elastin, suggesting that the intra-tumor microbiome could regulate elastin expression." (PMID 34359550, 2021). "In addition, a therapy that specifically targets elastin peptides would be a possibility to reduce tumor growth and invasion." (PMID 34827210, 2021). "Tumor cells are able to express, adhere, degrade, and migrate elastin proteins." (PMID 34827210, 2021). "In addition, the detected values (percentage of elastin) of each tumor strongly correlated with the RE data of in vivo MRI imaging (T1-weighted MR sequences) (y = 1.1304x − 0.7943, R = 0.877)." (PMID 34827210, 2021). "Interestingly, most of these genes have been implicated in general mechanisms of tumor biology, such as SERPINF1, reported as an inhibitor of angiogenesis and tumor suppressor, ASAP2, an EGFR pathway activator, or ELN and KRT8 related to the process of EMT." (PMID 34758873, 2021). "The major finding of this study is that molecular MR imaging using the elastin-specific probe enables the discrimination of the different tumor regions and the peritumoral matrix with a higher accuracy compared to conventional gadolinium-based contrast agents in VX2 hepatic tumors." (PMID 33247185, 2020). "In this study, we hypothesize that ELN is a key ECM protein regulating tumor growth and development in CRC." (PMID 32171282, 2020). "The hub gene lysyl oxidase encodes an ECM protein that increases insoluble matrix deposition and tissue stiffness by crosslinking collagens with elastin, and is essential to enable tumor cells to escape from primary sites and grow at secondary sites during metastasis." (PMID 32477405, 2020).
tumor (continued). "In the post hoc analysis, tumor areas showed significant differences between gadobutrol and elastin-specific contrast uptake in the tumor margin on day 14 (difference 1.86; P < 0.001), day 21 (difference 1.68; P = 0.007), and day 28 (difference 1.81; P < 0.001)." (PMID 33247185, 2020). "During tumor progression, elastin fragments are released in the tumor microenvironment." (PMID 33396696, 2020). "Elastin (ELN) is a component of ECM proteins involved in the tumor microenvironment." (PMID 32171282, 2020). "Degradation of basement membrane and interstitial connective tissues that contains mainly fibrillar collagens, and other ECM proteins such as proteoglycans, elastin, laminin, fibronectin etc. by enzymatic proteases around the tumor cells is an essential step for cancer invasion and metastasis." (PMID 31831717, 2019). "This characteristic is essential for the analysis of tumour tissues, which display alterations in the concentration and constitution of extra- and intracellular components, such as collagen, elastin, keratin, haemoglobin, and NADPH, leading in some cases to substantial autofluorescence." (PMID 29545609, 2018). "Furthermore, elastin peptides regulate tumor cell migration and invasion through an Hsp90-dependent mechanism." (PMID 26869928, 2016). "Thus, in this environment, expression of LOX protein should have a marked impact on the surrounding stroma, driving the cross-linking of collagen and elastin in the tumor microenvironment." (PMID 26077591, 2015). "Members of this family are responsible for the development of cross-links in extracellular matrix proteins, such as collagens and elastin, and may play a role in tumor progression." (PMID 25537509, 2015). "The angiostatic molecule endostatin has been reported to accumulate on elastin fibres, and this could reduce angiogenesis and hence tumour growth and spread." (PMID 25522915, 2014). "MMP-10 (also known as stromelysin 2) is generally limited to epithelial cells and can target pro-MMP-1, -7, -8, -9, -13, collagen type III, IV, V, gelatin, elastin, fibronectin, proteoglycans and laminin, activities that have been shown to promote tumor cell invasion." (PMID 24885595, 2014). "In addition, the mean number of elastin stains per case increased from 0.10 (SE, 0.41) to 2.51 (2.06) (p < 0.001), while the mean number of tumor-containing blocks per case remained constant [8.28 (6.69) vs. 8.12 (4.07); p = 0.761]." (PMID 25601902, 2014). "Also, significantly improved recurrence free survival was observed in tumours with high elastin content." (PMID 25522915, 2014). "Furthermore, nests of malignant epithelial tumor cells are shielded by layers of extracellular matrix (ECM) proteins (e.g., collagen, elastin, fibronectin, laminin) whereby tumor vasculature rarely penetrates into the tumor nests." (PMID 23898462, 2013). "Elastin peptides regulate several biological functions such as chemotaxis, proliferation, proteases synthesis in normal and tumor cells suggesting that they are involved in tumor progression and vascular pathologies." (PMID 21103358, 2010). "Besides degrading endocytosed unwanted proteins, cathepsins are critical in degrading extracellular matrix collagen, laminin, fibronectin, and elastin, thus playing essential roles in tumor growth." (PMID 21085595, 2010). "Cathepsin B, secreted by invading tumor cells, can degrade collagen and elastin." (PMID 15642138, 2005). "However, the composition of Matrigel differs from that found in the tumour microenvironment (e.g., complexes containing structural proteins such as collagen and elastin), making it difficult to faithfully reproduce ECM components derived from specific tissues or cell types." (PMID 41381717, 2025). "Although elastin staining has shown to increase interobserver agreement with regard to venous invasion, it would have to be investigated whether the use of this technique would lead to a different final classification when classifying tumor nodules." (PMID 34480612, 2021).
tumor (continued). "Especially in the area of targeted therapies of tumor associated ECM components or cancer to stroma signaling cross-talks, such as sorafenib and erlotinib, elastin-specific molecular imaging could act as a potential imaging biomarker to demonstrate the tumor responsiveness to the therapeutic agent." (PMID 33247185, 2020). "In addition, the infiltration of the skin by neoplasia will inevitably replace elastin fibers with neoplastic cells, which may also alter the effects of surgical excision on the skin." (PMID 24688882, 2014). "Finally, unpublished results from a survey of North American pathologists revealed that 46.5% of Canadian GI pathologists (20/43) routinely performed an elastin stain on at least one tumor-containing block on every CRC resection compared to less than 2% (1/58) of US GI pathologists." (PMID 25601902, 2014). "The resulting values reveal a more balanced elastin-to-collagen ratio in normal lung tissue (ECI close to 0), whereas the tumor region exhibits a significantly higher index, approaching." (PMID 40895158, 2025). "Other proteins present here are involved in matrix remodeling, which can alter tumor invasiveness (MMP13, S100A8, S100A9, and ELN)." (PMID 40699804, 2025). "It is well known that in transformed phenotypes, MMP-2 enables tumor invasion and angiogenesis via the degradation of ECM components like collagen, fibronectin, laminin, and elastin." (PMID 40724848, 2025). "LOX catalyzes the cross-linking of elastin and collagen in the extracellular matrix (ECM) and promotes the formation of tumor cell migration and metastasis." (PMID 40396123, 2025). "MMP12 secretion at nerve‐tumor interfaces degrades the neural ECM (e.g., elastin), facilitating cancer cell invasion along axons." (PMID 40985319, 2025). "During tumor progression, MMP-9 facilitates the invasion of tumor cells into the basement membrane by degrading specific substrates such as gelatin, elastin, and collagens, thereby promoting tumor metastasis and dissemination." (PMID 39188682, 2024). "This protein catalyzes the first step in the formation of crosslinks in collagens and elastin and is, therefore, involved in ECM assembly and the regulation of the PC tumor microenvironment." (PMID 39149513, 2024). "Meanwhile, Rbfox3 and SFRTM2 levels were downregulated while the levels of the fibrosis markers HGF, HMOX1, ELN, and GREM1 were upregulated in the tumor microenvironment of NEPC." (PMID 37240308, 2023). "Conversely, ELN, EFEMP1, and UCHL1 were expressed at low levels, whereas TP63 was expressed at high levels in tumor tissues in contrast with ANT." (PMID 37441420, 2023). "The ECM, which is one of the main components of TME, is composed of various molecules such as collagen, elastin, laminin, fibronectin, and the MMP that play a central role in tissue remodeling and supporting tumor growth." (PMID 38062443, 2023). "Several factors, including EZH2, SFTPC, IGFBP5, ELN and EDN2, are regulated by NFIB, which have considerate values in the tumour microenvironment, advancing cancer impulsiveness, angiogenesis, migration and spread." (PMID 37845675, 2023). "ELN, EFEMP1, and UCHL1 were expressed at low levels whereas TP63 was expressed at high levels in tumor tissues in contrast with ANT." (PMID 37441420, 2023). "As neoplasia results in degradation of the ECM by matrix metalloproteinases, the more exaggerated decrease of elastin in OSSN tissue would also be unsurprising." (PMID 35326744, 2022). "After the MMPs are activated, the insert can be combined with gelatin, collagen and elastin, crack the degraded ECM, adjust tumor cell adhesion, and promote angiogenesis and cell invasion." (PMID 35929837, 2022). "We found that only five genes (MITF, CCR7, JAK1, ELN, and SLC6A4) functioned as tumor suppressors, whereas the remaining 17 genes functioned as oncogenes." (PMID 36425071, 2022).
tumor (continued). "While the composition of the tumor ECM depends on the type of tumor, the most common molecules expressed by solid tumors are fibrillar collagens, fibronectin, elastin, and laminins." (PMID 35155581, 2022). "An interaction between the tumor cells and the ECM protein elastin is mediated by two elastin-binding proteins (S-gal and galectin-3) and two laminin receptors." (PMID 34827210, 2021). "Among the genes upregulated in the atypical tumor compared to the nevus were: SOX10, the receptor tyrosine kinases ROS1 and NTRK3, PLA2G2A, and HOXA11, while DUSP2, PDGFD, and ELN were downregulated." (PMID 35052351, 2021). "Elastin gene expression was found to be increased in patients with CRC tumors compared to the control group and adjacent non-tumor colon tissue." (PMID 34827210, 2021). "In a recent study, an elastin-specific contrast agent was used to visualize VX2-hepatic tumors in a rabbit model, and the use of the molecular agent to differentiate specific tumor and peritumoral regions based on its ECM composition was confirmed." (PMID 34827210, 2021). "CXCL5, ELN, JUN, and FGFR4 were highly expressed in normal tissues, while PLAU, RNASE7, JAG1, SPP1, and TNFRSF18 were highly expressed in tumor tissues." (PMID 32699529, 2020). "During cancer progression, tumor cells induce the expression of MMPs, such as MT1-MMP and MMP-2, which degrade ECM macromolecules like elastin and release EDPs, such as AG-9, that in turns stimulate MMP secretion, leading to an auto-amplification loop." (PMID 33396696, 2020). "However, in abnormal tissues, elastin fibers have almost disappeared, and collagen fibers are sparse and disrupted because malignant cells would secrete extracellular enzymes to degrade the original tissue architecture and promote tumor progression into surrounding tissues." (PMID 30940105, 2019). "Previous studies have reported that major aspects of skin damage induced by UV light include epidermal thickening and changes in extracellular matrix proteins (ECM) in the dermis, such as collagen and elastin remodeling." (PMID 30901885, 2019). "Tumor exterior dermal constituents like elastin fibers and some skin appendages appear brighter in TPEF, whereas the adjacencies of the tumor nests display a weaker TPEF intensity than the tumor cell agglomerates." (PMID 27429131, 2013). "Elastin staining confirmed the invasive nature of these tumors, as there was a lack of elastin fibers around the tumor, unlike in normal ducts." (PMID 41120769, 2025). "However, in our experiment, low doses of YWP showed significant effects in reducing MMPs and promoting the transcription of elastin, type I collagen, and type III collagen genes, indicating the effective role of YWP in combating skin photoaging." (PMID 39200548, 2024). "NRP1 is a potential molecule that can modify the tumor microenvironment (TME) and innate immune system in a targeted way to produce an efficient anti-tumor immune response, which binds to and uptakes neutrophil elastin on a number of BRCA cell lines." (PMID 36911389, 2023). "The expression of collagen I, fibrinogen, elastin, fibronectin, and vitronectin in tumor tissues from patients with the recurrent and non-recurrent disease was determined using immunohistochemistry." (PMID 37369642, 2023). "If the elastin pattern in the malignancy resembles the preexisting condition, the structural alterations are most likely due to the condition and not the tumor." (PMID 37894944, 2023). "Several matrix metalloproteinases (MMPs) were up-regulated in tumour samples, namely MMP12 (5.1-fold), MMP14 (2.3-fold) and MMP2 (2.2-fold), which cleave elastin (and insulin), collagen (and other extracellular proteins, such as aggrecan) and certain collagens (and gelatin), respectively." (PMID 37397358, 2023).